Y_RNA (Y RNA )
Gene: Miscellaneous RNA gene on chromosome 12 (8,592,476 to 8,592,585, forward strand). Ensembl gene ENSG00000238943.
Homologues: Orthologues: chimpanzee Y_RNA (98% identical). Paralogues in human: Y_RNA (85% identical), RNY1P5 (83% identical), Y_RNA (83% identical), Y_RNA (82% identical), Y_RNA (81% identical), Y_RNA (80% identical), Y_RNA (79% identical), RNY1 (78% identical), RNY1P1 (78% identical), Y_RNA (78% identical), RNY1P14 (77% identical), Y_RNA (77% identical), and 90 more.